INS (insulin)
Diseases named in the same sentence as INS in open-access papers (continued):
Sharing a sentence is not in itself a finding about the gene and the disease.
Insulin resistance (continued). "The tight relationship of BCAAs to metabolism in skeletal muscle, the most important tissue for insulin resistance, might also explain the strong correlations between 3-HIB and 2 h OGTT glucose and insulin, HOMA-IR, and HbA1c that we found." (PMID 29967793, 2018). "A recent meta-analysis from 22 RCTs involving a total of 11,402 subjects showed that fibrate administration decreased fasting plasma glucose (−5 mg/dL), insulin levels (−0.56 μIU/mL), and insulin resistance (HOMA-IR: −1.09), but not HbA1C." (PMID 29662003, 2018). "Six weeks of taking of DP-enriched beverage resulted in increased production of proteins involved in the insulin secretion pathway only in people with insulin resistance, not in healthy ones." (PMID 30513929, 2018). "The PTP1B has a negative role in insulin signaling pathways, and its increased intracellular expression lead to insulin resistance in an animal model." (PMID 34466413, 2018). "The mangosteen group reported a significant improvement in insulin sensitivity (homeostatic model assessment-insulin resistance, HOMA-IR −53.22% vs. −15.23%, p = 0.004), and no side effect attributable to treatment was reported." (PMID 29747432, 2018). "Although obesity is typically associated with a constellation of metabolic abnormalities, including insulin resistance and dyslipidemia, not all people with obesity become insulin resistant." (PMID 29853530, 2018). "In addition, we found that olanzapine-induced body weight gain and insulin resistance actively influence the expression of TCF7L2 in liver and skeletal muscle, and elevated level of insulin determines the increased expression of TCF7L2 in adipose tissue." (PMID 29713286, 2018). "Furthermore, diet-induced obesity leads to insulin resistance accompanied by impaired glucose tolerance and insulin sensitivity, and we also found that HFD fed mice exhibited higher fasting glucose, insulin levels and glucose intolerance." (PMID 29342124, 2018). "Moreover, insulin resistance provides a therapeutic strategy to prevent, delay or treat T2DM, obesity, and metabolic syndrome by improving insulin sensitivity." (PMID 30574122, 2018). "We instead provide evidence that attenuated PAK phosphorylation and impaired GLUT4 translocation during palmitate‐induced insulin resistance can occur independent of defects in insulin‐stimulated Rac1‐GTP binding." (PMID 30592185, 2018). "More sophisticated tests, such as the estimated insulin resistance (HOMA-IR) or estimated insulin secretion (HOMA-B) did not significantly improve the discriminatory accuracy of the Framingham Offspring Study." (PMID 29507612, 2018). "It was shown that a supplement containing MI 1100 mg, DCI 27.6 mg and folic acid 400 μg was effective in improving insulin sensitivity in children with insulin resistance, although it did not reduce weight." (PMID 30513929, 2018). "Fatty acid (FA)-stimulated insulin secretion (FASIS) is reviewed here in contrast to type 2 diabetes etiology, resulting from FA overload, oxidative stress, intermediate hyperinsulinemia, and inflammation, all converging into insulin resistance." (PMID 29921789, 2018). "This is consistent with previous reports that defects in insulin-stimulated glucose transport in insulin resistance are not due to obvious defects in proximal insulin signalling." (PMID 29402381, 2018). "In a meta-analysis, magnesium supplementation resulted in a significant reduction in insulin resistance, but did not affect fasting glucose and insulin levels." (PMID 30025522, 2018). "Given with PI3K is a nodal point that incorporates various signaling pathways including insulin signaling, PI3K inhibition during development may further complicate actions in obesity and insulin resistance." (PMID 30158592, 2018). "A negative relation of PERI with the beta cell function in insulin resistance (measured with the disposition index) and with insulin sensitivity (measured with OGIS) was found in women with PCOS." (PMID 30158974, 2018).
Insulin resistance (continued). "The hypoxic dams had better glucose tolerance and insulin sensitivity compared with normoxic dams and failed to develop insulin resistance in late gestation." (PMID 30206264, 2018). "Therefore, the defects in insulin-stimulated GLUT4 translocation in MitoPQ-treated cells and in insulin resistance models appear to be specific to insulin action." (PMID 29599292, 2018). "In short, although there is enough insulin in the systemic circulation, there was not enough glucose clearance from the blood, which is otherwise called insulin resistance state." (PMID 30524684, 2018). "In our study, glucose, C-peptide, insulin concentrations and insulin resistance (HOMA IR) did not directly correlate with AAA diameter, as revealed by Pearson’s correlation coefficient closed to zero." (PMID 30429669, 2018). "Using a comparative cross-sectional study design in 2015, 27 normal weight (18<BMI<25) and 85 overweight/obese (BMI≥25) aged 18 and 35 underwent clinical measures of HOMA (IR) as insulin resistance and QUICKI as insulin sensitivity tools in Fatemezahra Infertility Research Center of Babol." (PMID 30197771, 2018). "Pathophysiological conditions such as insulin resistance, and impaired insulin secretion related to pancreatic islet lesions, are not completely understood in human T2DM owing to ethical and technical challenges in accessing human pancreatic islets." (PMID 29463026, 2018). "However, there was also a decrease in fasting NEFA concentration within the Cod-PC group, which is a strong regulator of insulin sensitivity, and NEFA concentration is inversely correlated with insulin resistance." (PMID 29874805, 2018). "Molecular mechanisms of the attenuation of insulin resistance include facilitated glucose transporter type-4 (GLUT-4) expression and glucose uptake, as well as increased insulin-stimulated phosphorylation of insulin receptor-β (IR-β) and insulin receptor substrate-1 (IRS-1)." (PMID 30336561, 2018). "After 12 weeks of treatment with melatonin (3 mg/day), homeostasis model assessment insulin resistance index (HOMA-IR) (8.99 ± 5.10 versus 7.77 ± 5.21, p < 0.05) and fasting insulin (37.09 5 ± 20.26 μU/ml versus 32.10 ± 20.29 μU/ml, p < 0.05) were significantly decreased." (PMID 29706998, 2018). "Protein-tyrosine phosphatase 1B (PTP1B) negatively regulates insulin signaling pathways and plays an important role in T2DM, as its overexpression may induce insulin resistance." (PMID 30558294, 2018). "Insulin resistance refers to the condition where the insulin is not very effective in the conversion from glucose to lipid, which gives rise to high blood glucose levels." (PMID 30538754, 2018). "In contrast to the HFD-induced obese-insulin resistant model, the genetically induced obese-insulin resistant models, such as ob/ob mice and Zucker diabetic fatty rats, developed peripheral insulin resistance without brain insulin resistance." (PMID 30233495, 2018). "We conclude that elevated mitochondrial oxidants rapidly impair insulin-regulated GLUT4 translocation and significantly contribute to insulin resistance and that MitoPQ is an ideal tool for studying the link between mitochondrial oxidative stress and regulated GLUT4 trafficking." (PMID 29599292, 2018). "Selection of women who have a more severe PCOS phenotype due to the contribution of insulin resistance and/or hyperinsulinemia would explain why studies usually found that PCOS women display lower insulin sensitivity than controls on average, even within BMI subgroups." (PMID 29971102, 2018). "Moreover,FBS and insulin levels, as well as calculated HOMA-IRas an index of insulin resistance, were significantly lowerin the quercetin group compared with the placebo group." (PMID 29105398, 2018).
Insulin resistance (continued). "While the phenotypic insulin resistance in NAFLD would be expected to counteract insulin-mediated SREBP1c activation, a state of selective insulin resistance ensures that insulin retains its ability to promote DNL through SREBP1c while being unable to suppress gluconeogenesis." (PMID 29936596, 2018). "Although the evaluation of insulin resistance in dairy cows determined primarily by RQUICKI in previous studies is enough, in the present study, to further investigate the insulin sensitivity of cows with fatty liver, the hepatic insulin signaling pathway was examined." (PMID 29882814, 2018). "Modest changes were seen in glycemic parameters: only the 0.2 mg dose significantly reduced the HOMA-insulin resistance score with no significant changes in fasting glucose, insulin, glycated albumin and HbA1c." (PMID 29662003, 2018). "The adiponectin/TNF-α ratio showed negative correlations with insulin resistance (r=-0.68, p<0.001) and triglyceride (r=-0.39, p=0.014) and a positive correlation with insulin sensitivity (r=0.69, p<0.001)." (PMID 29387323, 2018). "We therefore investigated the effect of mangosteen on obese insulin resistant female subjects for 26 weeks and found a striking effect on insulin resistance, whereas glucose levels at 26 weeks were not significantly changed." (PMID 29747432, 2018). "In insulin resistance, the target cells fail to respond to ordinary levels of circulating insulin thus higher concentrations of insulin are required for a normal response." (PMID 30170598, 2018). "If insulin resistance or disturbance of InsR occurs, GSIS-related signalling pathways may be affected and β-cell dysfunction may occur, including disturbances in insulin synthesis and secretion." (PMID 29587416, 2018). "Both TTFA and malonate improved insulin-stimulated HA-GLUT4 translocation to the PM in all models of insulin resistance tested, albeit not to the same level as observed in control cells." (PMID 29402381, 2018). "In obese HF‐fed mice, antibiotic treatment lowered insulin and insulin resistance, but did not alter circulating monocyte characteristics." (PMID 30548217, 2018). "Whilst the indicated model is recognized as a physiologically relevant model of human pre-diabetic insulin resistance, dietary effects independent of insulin sensitivity must also be considered." (PMID 29249964, 2017). "Fasting blood-glucose (FBG), fasting insulin (FINS), glycosylated hemoglobin HBA1c, 2-h postprandial blood glucose (2hPG), Homa beta cell function index (HOMA-β), homeostasis model assessment of insulin resistance (HOMA-IR) and FE-1 were collected." (PMID 29078749, 2017). "For individuals in the VLBW group versus the control group, HOMA parameters indicated increased insulin resistance by increased HOMA‐IR (1.61 ± 0.09 vs. 1.40 ± 0.08, P < 0.016) and reduced HOMA‐%S (71.6 ± 3.5 vs. 85.9 ± 4.1, P < 0.016), a measure of insulin sensitivity." (PMID 29038359, 2017). "Since more than 80% of insulin-mediated glucose disposal during the euglycemic insulin clamp took place in skeletal muscle, these results indicated that the lowering plasma glucose concentration in T2DM significantly improved muscle insulin resistance." (PMID 28511711, 2017). "Briefly, 3 months post-surgery, significant improvements were observed in BMI, body fat percentage, cholesterol, low-density lipoprotein (LDL), fasting plasma glucose (FPG), fasting serum insulin (FSI), and homeostatic model assessment for insulin resistance (HOMA-IR)." (PMID 28883895, 2017). "Second, our results are based on analyses of insulin levels measured through fasting insulin rather than an index of insulin resistance such as the homeostasis model assessment of insulin (HOMA-IR)." (PMID 28323845, 2017). "This impairment in glucose tolerance in the evening is the result of reduced insulin secretion, as well as peripheral and hepatic insulin resistance, which occurs independent of the sleep/wake and feeding/fasting cycles." (PMID 28257081, 2017).
Insulin resistance (continued). "In this case, the use of indices of insulin sensitivity, such as the homeostatic model assessment for insulin resistance (HOMA-IR) and quantitative insulin-sensitivity check index (QUICKI) indices, would lead to the conclusion that insulin sensitivity is improved in KD fed mice." (PMID 28534852, 2017). "Although fructose does not increase insulin acutely, the long-term consumption of fructose seems to result in insulin resistance." (PMID 28555043, 2017). "Insulin resistance is a condition in which cells, tissues or a whole organism do not regularly respond to insulin, requiring higher amounts of the hormone to obtain the expected biological effect." (PMID 28642705, 2017). "Moreover, in subjects with type 2 diabetes, it has been shown that baseline serum AGEs correlate with fasting insulin, and indexes of insulin resistance, and an AGE-restricted diet for 4-months improves insulin sensitivity." (PMID 28426788, 2017). "Adiponectin knockout mice developed hepatic but not peripheral insulin resistance, which was evaluated with the euglycemic insulin clamp technique." (PMID 28786989, 2017). "The relationship of low serum 25OHD levels and insulin resistance and metabolic syndrome has been more consistently reported, although prospective studies do not always suggest improvements in insulin sensitivity with improvements in vitamin D status." (PMID 28272298, 2017). "Obesity can lead to insulin resistance, which is a condition in which a cell, tissue, or organism fails to respond appropriately to a given dose of insulin." (PMID 28587078, 2017). "In addition, MGO administration in vivo inhibits insulin secretion from isolated beta cells, due to decreased PDX-1 levels, and results in higher levels of MGO-derived AGEs and insulin-resistance in muscle, liver, and adipose tissue." (PMID 28106778, 2017). "Type 2 diabetes (T2D) is a complex disorder characterized by high blood sugar, insulin resistance, and relative lack of insulin." (PMID 29099854, 2017). "Insulin resistance has been reported to be associated with NAFLD regardless of glucose levels and patients with NAFLD have reduced insulin sensitivity in the muscle, liver, and adipose tissue." (PMID 28702206, 2017). "Differentiation of preadipocytes isolated from SAT but not VAT correlated inversely with insulin resistance as measured by HOMA or fasting insulin." (PMID 28151993, 2017). "Because of the recognized contributions of dyslipidemia and inflammation to insulin resistance, we sought to test if TKI-mediated inhibition of RIPK2 could attenuate NOD1-induced impairments in insulin signalling in adipocytes." (PMID 28484277, 2017). "It said that a significant effect of Mg supplementation was observed on Homeostatic Model Assessment and Insulin Resistance index, but not on plasma glucose, HbA1c, and insulin." (PMID 28296769, 2017). "Fat/weight ratio, insulin and homeostasis model assessment of insulin resistance were not influenced by either maternal or weaning diet." (PMID 28706733, 2017). "In conclusion, our study supports that fructose is a more potent inducer of insulin resistance, and HFCS may elicit greater detrimental effects on insulin sensitivity than SUC." (PMID 28629187, 2017). "Twenty individuals had quantification of systemic insulin resistance (IR) via the steady-state plasma glucose (SSPG) test as originally described and validated, and twelve of those individuals were classified as insulin resistant (SSPG greater than 140 mg/dL)." (PMID 28081144, 2017). "Insulin resistance testing, as well as free fatty acid, glucose and insulin measurements, exhibited no significant change after GH replacement." (PMID 28670222, 2017). "As mentioned in our study, complement C3 and serum insulin concentrations and insulin resistance were higher in NWO than those in non-NWO subjects." (PMID 29299442, 2017).
Insulin resistance (continued). "Since type 2 diabetes (T2DM) is characterized with impaired glucose intolerance and insulin resistance, the oral administration of glucose (OGTT) and intraperitoneal insulin tolerance test (IPITT) were employed to roughly assess the beneficial metabolic phenotype of Rb2." (PMID 28534819, 2017). "Type 2 diabetes mellitus (T2DM) is well known as a complex multifactorial chronic metabolic disease that is characterized by a lack of adequate insulin or insulin resistance, resulting in hyperglycemia." (PMID 29404372, 2017). "For example, the serum glucose concentration decreased from 127 mg/dL to 110 mg/dL, the proportion of glycated haemoglobin declined from 7.7% to 6.7%, insulin resistance (HOMA-IR) decreased from 6.1 to 7.0, and serum insulin concentration decreased from 13.4 mcIU to 19.9 mcIU." (PMID 28829398, 2017). "We found that the lower GRS was associated with a greater decrease in fasting insulin, HbA1c, and insulin resistance as assessed by HOMA-IR, and a lesser increase in insulin secretion as assessed by HOMA-B, particularly among participants consuming a low-protein diet." (PMID 28387720, 2017). "Unlike retinol, moderate negative correlations with fasting insulin levels and the derived homeostatic model assessment for insulin resistance (HOMA-IR) index were observed in the α-tocopherol network." (PMID 28194237, 2017). "Interestingly, AD has insulin and IGF-1 resistance with dysfunctional IRS-1 mediated insulin resistance." (PMID 28505155, 2017). "Using paired samples of VAT and SAT explants of patients with different BMI, we observed a metabolic reprogramming independent of the presence of insulin and thus, likely autonomous from insulin resistance or hyperinsulinemia." (PMID 28567337, 2017). "The induction of GLUT4 translocation in the absence of insulin by phytochemicals, known as insulin mimetic compounds, is a reasonable strategy to combat the effects of insulin resistance." (PMID 28777818, 2017). "In keeping with insulin resistance in adipose tissue, decreased phosphorylation of Akt was seen in response to insulin in perigonadal WAT and interscapular BAT, but not in the liver or muscle of aP2FAK−/− mice compared with control littermates." (PMID 28165007, 2017). "In addition, the homeostatic model assessment-insulin resistance (HOMA-IR) and quantitative insulin sensitivity check index (QUICKI) were 3.8 ± 2.0 and 0.32 ± 0.02, respectively." (PMID 28805670, 2017). "Since mild uncoupling of the mitochondria could be beneficial in insulin resistance, we tested the effect of BGP-15, an insulin sensitizer on Δψ by using a Δψ-sensitive dye (R123) in isolated rat liver mitochondria." (PMID 28046125, 2017). "While insulin resistance and whole-body insulin sensitivity index did not greatly differ between PWS and obese controls, several anthropometric and metabolic differences existed between the two populations." (PMID 28600576, 2017). "As increased BMI impairs GLP-1 secretion and aggravates insulin resistance, the supraphysiological infusions of GLP-1 may act as a positive feedback signal in obese patients to improve insulin sensitivity and reduce chronic obesity." (PMID 29167470, 2017). "In humans, insulin resistance is also a potential negative effect, but some studies have shown improvements in insulin sensitivity." (PMID 28534852, 2017). "Lastly, the measurements, HOMA-IR, insulin, and GI ratio were conducted in fasting state, whereas euglycemic-hyperinsulinemic clamp tests insulin resistance in an insulin-stimulated state, but the data was not available in NHANES." (PMID 28835661, 2017). "Compared with CON, INT significantly decreased (P = 0.04) serum fasting insulin (Δ, 3.1 ± 10.7 pmol·L−1 for CON and −12.7 ± 18.7 pmol·L−1 for INT) and homeostasis model assessment of insulin resistance (HOMA2-IR; Δ, 0.06 ± 0.20 for CON and −0.23 ± 0.36 for INT)." (PMID 28753161, 2017).